NKG7 (natural killer cell granule protein 7)
Diseases named in the same sentence as NKG7 in open-access papers (continued):
Sharing a sentence is not in itself a finding about the gene and the disease.
systemic sclerosis (1 paper, 2025). A chronic disorder, possibly autoimmune, marked by excessive production of collagen which results in hardening and thickening of body tissues. "Thus, to compare the expression of NKG7 and CCL5 in systemic sclerosis versus healthy skin, systemic sclerosis T cells were binned together and compared as a group to healthy skin–derived T cells." (PMID 39989459, 2025). "This analysis revealed that there was no meaningful difference in the NKG7 or CCL5 expression in systemic sclerosis T cells versus healthy T cells; in fact, their expression was slightly lower." (PMID 39989459, 2025). "NKG7 T cells were also found to be clonally expanded in NL lesional skin, but only represented approximately 3% of the T cell repertoire in healthy skin and were not increased in systemic sclerosis lesional skin." (PMID 39989459, 2025).
Thrombocytopenia (1 paper, 2025). A reduction in the number of circulating thrombocytes. "For patients with low NKG7 expression, CD8+ T cell-mediated cytotoxicity could not be regarded as the main cause of thrombocytopenia." (PMID 40837024, 2025).
tumor (88 papers, 2018 to 2026). "In future studies, we will first investigate the potential of NKG7 expression as a biomarker for immunotherapy responsiveness and examine the existence of tumor subclones associated with immune evasion." (PMID 40422184, 2025). "The expression of NKG7/TIA-1 is critically linked to anti-tumor responses, particularly in CD8+ T cells." (PMID 41030456, 2025). "Clinically, NKG7 expression is associated with improved patient outcomes across various tumor entities." (PMID 40538191, 2025). "Effector lymphocytes mobilized by G-CSF + ISO, particularly effector-memory CD8 + T-cells and NK-cells, exhibited upregulated genes and enriched gene sets linked to anti-tumor activity (e.g. NKG7, GZMB, NK cells cytotoxicity)." (PMID 41194247, 2025). "It has been reported that low GZMB expression is associated with tumour metastasis.NKG7 is a complete membrane protein that is expressed in cytotoxic particles of lymphocytes, and it plays an important role in the development and metastasis of cancer." (PMID 35473583, 2022). "Together these data suggest that NKG7 deficient CD8+ T cells hypersecrete inflammatory cytokines during a prolonged immune synapse with tumor cell targets." (PMID 35874669, 2022). "The slow kill rate of NKG7 deficient T cells resulted in a significantly longer T cell-tumor cell synapse, thereby prolonging T cell stimulation, and consequently promoted hypersecretion of inflammatory cytokines." (PMID 35874669, 2022). "The 63 upregulated genes, including PLA2G2D, IFNG, LAG3, CD8B and NKG7, were associated with tumor immunity." (PMID 35530341, 2022). "In the setting of a tumor which is sensitive to cytokine-mediated death, cytokine hypersecretion by NKG7 deficient CD8+ T cells compensated for their inefficient synapse-mediated cytotoxicity, leading to a net-zero effect on overall tumor control." (PMID 35874669, 2022). "PLA2G2D, IFNG, CD8B and NKG7 were found to be significantly upregulated, which are associated with tumor immunity." (PMID 35530341, 2022). "Anti-MAA-clonotypes showed expression of genes that have been previously associated with tumor-specificity and cytotoxicity (e.g., NKG7, CCL5, TIM3), as in a previous analysis of anti-MAA and neoantigen-specific clones in a scRNA-seq data set16." (PMID 36220826, 2022). "Interestingly, cytokine hypersecretion enables NKG7-deficient CD8 T cells to eliminate their tumour targets." (PMID 41494240, 2026). "NKG7 deficiency results in reduced CD107a production and impairs tumor cell killing." (PMID 40837024, 2025). "Importantly, in vivo, the hypersecretion of TNF by NKG7 deficient CD8+ T cells compensates for reduced perforin-mediated control of MC38-OVA tumors through enhanced TNF-mediated tumor cell death." (PMID 35874669, 2022). "A number of these studies have highlighted that expression of the gene encoding natural killer granule associated protein 7 (Nkg7) in cytotoxic lymphocytes is associated with anti-tumor immunity, and reignited interest in this protein as a therapeutic target for improving cancer immunotherapy." (PMID 35874669, 2022). "However, as a result of inefficient cytotoxic activity, NKG7 deficient T cells form a prolonged immune synapse with tumor cells, resulting in increased secretion of inflammatory cytokines, including tumor necrosis factor alpha (TNF)." (PMID 35874669, 2022). "Interestingly, while our results showed that NKG7 strongly correlates with cytotoxicity‐associated transcripts in NK cells under steady‐state conditions, the usage of these transcripts appears to differ in tumor‐infiltrating NK cells." (PMID 40538191, 2025). "Studies have confirmed that NKG7 can increase the accumulation and activation of T cells in the tumor microenvironment." (PMID 40837024, 2025). "NKG7 expression is stable and consistently detected in cells across immunologically relevant tissues and within tumor‐infiltrating immune cells (right)." (PMID 40538191, 2025).
tumor (continued). "NKG7, primarily expressed by NK cells, plays a crucial role in controlling tumor initiation, growth, and metastasis." (PMID 41325308, 2025). "Taken together, these data demonstrate that NKG7 expression is maintained on tumor‐infiltrating immune cells in numerous malignancies." (PMID 40538191, 2025). "Genes associated with increased cytotoxicity (GZMB, GNLY, PRF1), and anti-tumor activity (NKG7) were upregulated in the cytotoxic lymphocytes, including CD8 + T cells, γδ T cells, NK cells, and ILCs." (PMID 41194247, 2025). "As such, NKG7 gene expression positively correlated with the overall cytotoxicity signature in tumor‐infiltrating NK cells." (PMID 40538191, 2025). "More recently, Nkg7 was found to be upregulated in intratumor antigen-specific CD8+ T cells and NK cells, with Nkg7-deficient mice exhibiting impaired control of tumour growth." (PMID 38881737, 2024). "Timer2.0 revealed that in LUSC, NKG7 was positively associated with CD8 + T cells and negatively associated with tumor purity." (PMID 38182561, 2024). "NK cell granule protein-7 (NKG7) has been reported to play an important role in anti-tumor immunity." (PMID 38182561, 2024). "The correlation with NKG7 was most significant under IgG treatment, which explained the significant anti‐tumor effect from NK cells." (PMID 38896792, 2024). "In pt115, the genes that were most upregulated in the expanded REP TIL clonotypes in the original tumor were NKG7, CCL5, and CD8A, but also those related to cytotoxicity, such as GZMB/H/K." (PMID 37484198, 2023). "Subsequently, we analyzed DEGs between tumor and normal tissues and selected the top five DEGs with the highest expression, which were SPP1, AKR1C2, AKR1B10, AGT, and EPHX1 in tumor tissues and NKG7, KLRD1, KLRB1, CCL5, and CST7 in normal tissues." (PMID 35967424, 2022). "Given recent evidence highlighting a role for NKG7 in anti-tumor immunity we examined the expression of NKG7/Nkg7 amongst immune cell subtypes in human and mouse samples using available RNA-sequencing datasets." (PMID 35874669, 2022). "Using this model system, we found that Nkg7-/- CD8+ T cells were capable of lysing tumor cell targets, but at a significantly reduced efficiency compared to Nkg7+/+ T cells." (PMID 35874669, 2022). "In this study, we add to the growing literature supporting a role for NKG7 in modulating CD8+ T cell cytotoxic activity against tumor cells." (PMID 35874669, 2022). "It should be noted that NKG7 expression was downregulated in one of the studies, but this particular study analyzed plaque and tumor stages together, making the interpretation of their results unclear." (PMID 34204115, 2021). "To further explore the basis for the concordant expression between AC008750.1 and NKG7, we sought to experimentally validate the putative effect of this immune-related lncRNA on the anti-tumour response." (PMID 33037279, 2020). "In AML, the trends for CD276, IDO1, and NKG7 all have substantially different intercepts and slopes than seen in the other tumor types." (PMID 29929551, 2018). "Indeed, within tumor‐infiltrating NK cells, NKG7—while highly expressed and a strong correlate of cytotoxicity signature—was surpassed by GZMA and PRF1 in terms of correlation with cytotoxicity score." (PMID 40538191, 2025). "Additionally, NKG7 was highly expressed in tumor‐infiltrating NK cells from all disease subsets analyzed." (PMID 40538191, 2025). "Although γδ T cells and CD4 T cells express cytotoxic genes (e.g., GZMB, NKG7), their activity may be suppressed by tumor-induced immune checkpoint signaling and metabolic competition." (PMID 40340807, 2025). "Within these tumor‐infiltrating NK subsets, NKG7 was consistently expressed." (PMID 40538191, 2025). "After showing that NKG7 is consistently expressed across tissues and a core constitute of the polyfunctional cytotoxic program, we next sought to evaluate cytotoxic molecule expression dynamics in tumor‐infiltrating immune cells." (PMID 40538191, 2025).
tumor (continued). "NKG7 (natural killer cell granule protein-7) is associated with the quantity and trafficking (as well as calcium release) of cytolytic granules within cytotoxic CD8+ T cells, which are essential for effective anti-tumor cytotoxicity." (PMID 40422184, 2025). "Upregulating NKG7 in CAR-T by lentivirus transduction could promote the cytotoxicity at low Met concentration, suggesting that NKG7 is crucial for the anti-tumor function of CAR-T." (PMID 38182561, 2024). "Low Met environment resulted in the reduction of m5C and the instability of NKG7 mRNA, which may contribute to the repression of the tumor-killing capacity of CAR-T." (PMID 38182561, 2024). "Tumor-specific IL-7Rhi CD8+ T cells (cluster 4) expressed intrinsic cytotoxic mediators including natural killer cell granule protein 7 (Nkg7), killer cell lectin receptor D1 (Klrd1), cathepsin W (Ctsw), cystatin F (Cst7), and Ccl5, suggesting a capacity for cytotoxicity." (PMID 37459511, 2023). "Interestingly, the single-cell transcriptome analysis showed the presence of cells expressing NKG7, a gene involved in granule exocytosis and highly involved in anti-tumor immunity." (PMID 37007090, 2023). "Recent studies have found that expression of NKG7 may enhance the efficiency of CD8+T cells to form immune synapses with tumor targets and trigger cell death." (PMID 37898694, 2023). "Collectively these data demonstrate that reduced cytotoxic activity via the perforin-granzyme pathway in the absence of NKG7 can be compensated by TNF-mediated tumor cell death due to hypersecretion of TNF by NKG7 deficient T cells." (PMID 35874669, 2022). "More recently, a role for NKG7 in regulating anti-tumor immunity has been reported." (PMID 35874669, 2022). "In comparing the occurrence and development of normal tissues and tumor tissues, we found that the expression levels of genes encoding activation and cytotoxic molecules, such as GZMB, GZMH, GZMK, GZMA, and NKG7, increased significantly and had strong correlations with signs of exhaustion." (PMID 35634956, 2022). "However, anti-PD-L1 treatment resulted in upregulation or downregulation of numerous genes in CD45+ tumor-infiltrating immune cells in TCh3 tumors, including Cd3d, Cd3e, Cd3g, Cd8a, Cd8b1, Nkg7, Ccl5, Ets1, Icos, Cxcr6, Pdcd1, Lag3, Prf1, and Gzmb (right)." (PMID 35366939, 2022). "However, after 30 minutes, a significantly higher frequency of conjugates was observed in Nkg7-/- T cell-tumor co-cultures, suggesting these cells remain synapsed for longer than Nkg7+/+ T cells." (PMID 35874669, 2022). "Given Nkg7-/- CD8+ T cells retain the capacity to form an immune synapse with a tumor target, we next examined whether they exhibited any temporal differences in synapse formation compared to control Nkg7+/+ CD8+ T cells." (PMID 35874669, 2022). "To further assess if NKG7 enhances the rate of tumor killing, we co-cultured Nkg7+/+ or Nkg7-/- T cells with anti-CD3/28-coated P815 targets cells at a ratio of 1 T cell (effector) to 5 tumor cells (targets) and measured the percent of tumor targets killed overtime for 12 hours." (PMID 35874669, 2022). "A recent study showed that NKG7 is a regulator of lymphocyte granule exocytosis and downstream inflammation in many diseases, and the NKG7 expression of natural killer cells is essential for the control of tumor initiation, progression, and metastasis." (PMID 34777632, 2021). "Finally, siRNA-mediated knockdown of AC008750.1 significantly impaired both the expression of NKG7 and the anti-tumour capacity of NK cells." (PMID 33037279, 2020). "Indeed, NKG7 is the strongest correlate of cytotoxicity across tumor‐infiltrating immune cells." (PMID 40538191, 2025). "In the tumor environment and in the circulation of patients, CD4+ cytotoxic T lymphocytes (CTLs) express cytolytic effector molecules, including granzymes, perforin, and other granule-associated proteins such as natural killer cell granule Protein 7 (NKG7) and granulysin." (PMID 39507526, 2024).
tumor (continued). "Gene signatures associated with NK‐cell cytotoxicity and activation (Gzma, Prf1, Klrd1, Nkg7, and Klrk1) were markedly upregulated at high proportions of NK cells in nanoSTING@Mn combined with LLL on dLNs and Tumor, as compared to nanoSTING@Mn alone (bottom)." (PMID 41126739, 2026). "Among other roles, NKG7 enhances CD8 T cell synapse efficiency and, thus, CD8 T cell killing of tumour targets." (PMID 41494240, 2026). "Cytotoxic/effector genes (GNLY, GZMA, GZMK, IFNG, NKG7, PRF1) were primarily expressed by T and NK cells, with notable upregulation in stRNA‐seq‐defined invasive front and tumor core regions." (PMID 41057994, 2025). "Among these, GZMK+ CD8+ T cells, GZMB+ CD8+ T cells, and NK cells exhibited high levels of effector cytotoxic genes such as GZMA, GZMB, NKG7, PRF1, and GNLY, contributing significantly to anti-tumor immunity." (PMID 40149859, 2025). "Canonical markers were used to annotate different cell types: malignant cells (COL1A1, IBSP), myeloid cells (CD74, CD14), osteoclasts (CTSK, MMP9), pericytes (RGS5, ACTA2), endothelial cells (PECAM1, VWF), and tumor-infiltrating lymphocytes (CD3D, NKG7)." (PMID 40730548, 2025). "We identified the expression of NKG7 by immune cells, as well as TFPI2 and PIGR in the tumor area, as potential biomarkers that predict recurrence and survival of patients with HGSC." (PMID 40422184, 2025). "ITGAE is associated with a group of genes that have a cytotoxic function in CD8 cytotoxic T cells (CTSW, GNLY, NKG7, PRF1, GZMB, KLRK1) up-regulated in the tumor, identifying resident CD8 T cells in the tumor to have a highly cytotoxic and activated phenotype." (PMID 39548591, 2024). "We also found that several key cytotoxic genes (such as NKG7, GNLY, PRF1) were more highly expressed in the non-tumor regions." (PMID 38123589, 2023). "Our data highlights the complex role of NKG7 in both direct tumor cell lysis and inflammatory responses underscoring CD8+ T cell anti-tumor immunity." (PMID 35874669, 2022). "We observed that the expression of NKG7, GZMH, GZMA and GZMB in tumor-infiltrating CD8+ CTSW+ cytotoxic cells were significantly increased in female patients, indicating that these T cells have a stronger antitumor cytotoxic effect." (PMID 36172359, 2022). "Cytotoxicity-related genes GNLY, NKG7, GZMB and GZMA were downregulated in both tumor-derived CD4+ and CD8+ T cells." (PMID 36506053, 2022). "NKG7, KLRD1, and KLRB1 are marker genes of T cells and NK cells, which is in line with the fact that the proportions of T and NK cells in tumor samples were significantly smaller than those in paracancerous tissues." (PMID 35967424, 2022). "The immune cytotoxic/effector genes were mainly expressed by T and NK cells, some of which were commonly up‐regulated in the inflammation and tumor regions in the Stereo‐seq slides, including GNLY, GZMA, GZMB, and NKG7." (PMID 35986392, 2022). "We found that 47 genes were upregulated in tumor tissues compared to normal tissues, such as CD48, TIGIT, GNLY, CCL19, CCL5, CXCL13, CCL17 and NKG7." (PMID 36713530, 2022). "In particular, six tumor cytotoxicity-related molecules (GZMA, GZMB, GZMH, IFNG, FASLG, and NKG7) from T cells had significantly higher levels in the BM than in PB." (PMID 40977909, 2022). "The expression of NKG7 is highly correlated with cytotoxicity and CD8+ T cells, and NKG7 was upregulated in tumour-specific CD8+ T cells." (PMID 35473583, 2022). "For CD8+ T cells, although the cytotoxic molecules (GZMA, GZMB, NKG7, and PRF1) were highly expressed, a fraction of CD8+ T cells showed positive with exhaustion biomarkers (CTLA4, PDCD‐1, and TIGIT), indicating their tumor‐cytotoxic activity was constrained." (PMID 34185421, 2021). "We previously showed that NKG7 marks resilient T cells that are critical to ICI response and, conversely, that Bim (BCL-2-interacting mediator of cell death) is upregulated in T cells by PD-L1/PD-1 engagement and drives poor anti-tumor immunity." (PMID 40082438, 2025).